TGFBR3 (transforming growth factor beta receptor 3)
Diseases named in the same sentence as TGFBR3 in open-access papers (continued):
Sharing a sentence is not in itself a finding about the gene and the disease.
Stroke (6 papers, 2009 to 2024). Sudden impairment of blood flow to a part of the brain due to occlusion or rupture of an artery to the brain. "We also observed sex-specific alterations in other EndMT-associated genes; male MMP-3 KO stroke brains showed downregulation of Tgfbr3 and the major EMT-associated transcription factor Snai2." (PMID 39000490, 2024). "Several other studies also showed that the TGFBR3 rs284875 SNP had been linked with increased stroke risk." (PMID 35781614, 2023). "SNPs in the ANXA2, TEK and TGFBR3 gene loci were associated with stroke risk, the TGF-β/BMP pathway is associated with several SCD subphenotypes, while polymorphisms within the UGT1A1 are associated with increased serum bilirubin levels and cholelithiasis." (PMID 34071035, 2021). "Stroke is also directly associated with variants in TGFBR3 and indirectly associated with variants in transforming growth factor, beta receptor II (TGFBR2), which have essential, non-redundant roles in TGF-betạ signaling." (PMID 20401335, 2009). "Stroke has been directly associated with variants in the TGFBR3 gene; further investigations of this gene may help define specific mutations that actually affect biological functions and confer stroke risk or protection in children with SCD." (PMID 35781614, 2023). "Key EMT-related genes that were downregulated upon MMP-3 KO in male stroke brains included Fbn1, Fbln1, Tgfb1, Tgfbr3, Snai2, and Fgf2." (PMID 39000490, 2024). "Among SNPs linked to stroke risk in SCD patients, the rs284875 SNP residing within the TGFBR3 gene has been linked with cerebrovascular disease." (PMID 35781614, 2023). "This network of interactions included three genes, BMP6, TGFBR2, TGFBR3 with a functional role in the TGF-beta pathway and one gene (SELP) associated with stroke in the general population." (PMID 20401335, 2009). "Five single nucleotide polymorphisms (SNPs) tested in children with SCD were significantly associated with stroke risk, namely ANXA2 (rs11853426), TEK (rs489347), and TGFBR3 (rs284875) variants, whereas ADCY9 (rs2238432) and ∝ -thalassemia were linked with decreased stroke risk." (PMID 35781614, 2023). "Although our review of the literature does not suggest that his infarct can be explained by the factor V Leiden heterozygosity, he was not tested for any of the other genetic variants that have been recently found to be associated with stroke in SCD such as ANXA2, TGFBR3, and TEK." (PMID 23972124, 2013). "Also, there have been a few single nucleotide polymorphisms (SNPs) in persons with SCD that have been found to be associated with increased stroke risk: ANXA2, TGFBR3, and TEK were noted in a study including these SNPs." (PMID 23972124, 2013). "Key EMT-related genes that were downregulated in MMP-3 KO males included Fbn1, Fbln1, Tgfb1, Tgfbr3, Snai2, and Fgf2, while female MMP-3 KO stroke brains showed downregulation of Fbln5, Fbln1, Fbln2, and Tgfb1." (PMID 39000490, 2024).
bladder cancer (5 papers, 2019 to 2025). "Polymorphisms in gene TGFBR3 have been linked to several diseases, such as Marfan syndrome, bladder cancer, Behçet's disease, and SCD." (PMID 33149723, 2020). "Another study showed that TGFBR3 can inhibit the proliferation and migration of bladder cancer cells." (PMID 39404708, 2024). "In the literature, polymorphisms in TGFBR3 have been associated with inflammatory diseases other than SCD, such as Marfan syndrome, bladder cancer, and Behçet's disease." (PMID 33149723, 2020). "Similar tumor suppressor functions for TGFBR3 have also been reported for renal cell carcinoma, endometrial carcinoma, and bladder carcinoma, among others." (PMID 31803141, 2019).
colon cancer (5 papers, 2019 to 2024). "Increases of TGFBR3 enhanced ligand-stimulated anchorage-independent growth and migration of colon cancer cells while modestly increasing tumorigenesis of xenografted animals." (PMID 32471132, 2020). "In contrast to its tumor-suppressive role, TGFBR3 promotes oncogenesis in colon cancer and triple-negative breast cancer." (PMID 32471132, 2020).
endometrial cancer (5 papers, 2019 to 2024). Primary or metastatic malignant neoplasm involving the endometrium (mucous membrane that lines the endometrial cavity). "An additional mechanism with potential impact on the declined expression of the TGFBR3 gene involves three intronic SNPs, i.e., rs12566180 (c.-114 + 2392C > T) and rs2296621 (c.2285 − 99G > T), which correlate with TGFBR3 transcript loss in endometrial cancer." (PMID 34501347, 2021). "The rs12566180 (c.-114 + 2392C > T) and rs2296621 (c.2285 − 99G > T) polymorphisms significantly altered in endometrial cancer are located within intronic regions of the TGFBR3 gene, which may indicate their potential impact on transcription and stability of the primary transcript." (PMID 32987826, 2020).
gastric cancer (5 papers, 2020 to 2025). A primary or metastatic malignant neoplasm involving the stomach. "Cancer-associated fibroblasts-secreted SULF1 interfered with the interaction between TGF-β1 and TGFBR3 by combining with TGFBR3 on gastric cancer cell membrane, subsequently activated TGF-β signaling pathway." (PMID 38438372, 2024). "For instance, SULF1 secreted by CAFs binds to TGFBR3 on the surface of gastric cancer cells, alters its interaction with TGF-β1, and subsequently facilitates the activation of the TGF-β signaling pathway, thereby promoting metastasis and resistance to cisplatin." (PMID 40843362, 2025). "We found that DCLK1 expression significantly correlates with both TGFB1 and CXCL12 and their receptors TGFBR1, TGFBR2, and TGFBR3, and CXCR4, respectively, in colon and stomach cancer patients." (PMID 31979136, 2020). "Between the TGF-β family co-receptors (ENG and TGFBR3) implicated in cancer progression and inhibin function, ENG was more expressed, particularly in lung adenocarcinoma and gastric cancers, corresponding with ENG being a strong negative predictor of survival." (PMID 33819300, 2021).
myocardial infarction (5 papers, 2014 to 2024). Gross necrosis of the myocardium, as a result of interruption of the blood supply to the area, as in coronary thrombosis. "Therapeutic upregulation of TGFBR3 in cardiac fibroblasts by simvastatin has been reported to elicit beneficial anti-fibrotic action on fibroblasts and improved cardiac function after myocardial infarction." (PMID 38727290, 2024). "TGFBR3 expression is significantly upregulated in patients after myocardial infarction and may serve as a therapeutic target and biomarker for myocardial damage by activating p38 MAPK to induce cardiomyocyte apoptosis." (PMID 34868268, 2021). "In a sensitivity analysis, we performed a GWAS excluding self-reported cases of previous myocardial infarction (20 resettlers, 66 native Germans); the same SNPs from BTNL2 and TGFBR3 marked a genetic difference between the resettlers and native Germans." (PMID 34201265, 2021). "In genome-wide association studies, these genes have been identified in connection with myocardial infarction (DGKB); immune function, rheumatoid arthritis, and sarcoidosis (BTNL2); and bone mass in different ethnic groups (TGFBR3)." (PMID 34201265, 2021).
non-small cell lung carcinoma (5 papers, 2010 to 2021). A group of at least three distinct histological types of lung cancer, including non-small cell squamous cell carcinoma, adenocarcinoma, and large cell carcinoma. "TGFBR3 has been shown to act as a tumor suppressor in renal clear cell carcinoma and non-small cell lung cancers which was also confirmed here." (PMID 33819300, 2021). "In non-small cell lung cancer, TGFBR3 is also downregulated and promotes cancer cell migration and invasion." (PMID 31803141, 2019). "A recent study has proposed a novel mechanism whereby the high mobility group AT-hook 2 (HMG2A) transcript promotes non-small cell lung cancer progression by competing with transforming growth factor β receptor III (Tgfbr3) for let-7 binding." (PMID 28306719, 2017). "It has been reported that defective expression of TGFBR3 was found in non-small cell lung cancer (NSCLC)." (PMID 20677641, 2010).
ovarian carcinoma (5 papers, 2017 to 2024). A malignant neoplasm originating from the surface ovarian epithelium. "According to the literature data, polymorphism of the TGFBR3 gene is considered as a mechanism responsible for betaglycan down-regulation of HBV-infection related hepatocellular carcinoma and ovarian cancer." (PMID 32987826, 2020).
renal cell carcinoma (5 papers, 2019 to 2021). "Orthotopic inoculation experiments have shown that the loss of TGFBR3 promotes metastasis via TGF-β-dependent and -independent pathways in renal cell carcinoma cells." (PMID 34266418, 2021). "Low TGFBR3 expression is correlated with a poor prognosis in renal cell carcinoma patients." (PMID 34266418, 2021). "Additionally, decreased TGFBR3 expression enhances the metastatic ability and tumor growth of renal cell carcinoma cells suggesting that TGFBR3 mainly acts as a suppressor of cancer development." (PMID 32491253, 2020).
sickle cell disease (5 papers, 2020 to 2024). Sickle cell anemias are chronic hemolytic diseases that may induce three types of acute accidents: severe anemia, severe bacterial infections, and ischemic vasoocclusive accidents (VOA) caused by sickle-shaped red blood cells obstructing small blood vessels and capillaries. "Single nucleotide polymorphisms in the priapism in patients with sickle cell disease are associated with TGFBR3, AQP1, and integrin-αv." (PMID 39335570, 2024).
asthma (4 papers, 2020 to 2025). "All novel asthma lead variants had co-directional impact with at least nominal significance (p < 0.05) in both cohorts, although heterogeneity for 1p22.1 (harboring TGFBR3) was high (I2 = 76.3%)." (PMID 41213931, 2025). "Significant DMPs fall within genes involved in the TFG-β related pathways (e.g. BMP2, FLCN, ING2, PMEPA1, PRDM16, TGFB1I1 and TGFBR3), in line with previous studies that reported an association between these genes and the increased asthma risk." (PMID 35619695, 2022). "Other respiratory complications, such as asthma and bronchopulmonary dysplasia, have also been associated with TGFBR3 in the literature." (PMID 33149723, 2020). "Decreased levels of TGFBR3 were measured in lungs from severe COPD patients with emphysema and in blood of asthma patients compared to controls, which might be caused by increased levels of miR-223 in COPD and asthma patients." (PMID 32509795, 2020).
dementia (4 papers, 2021 to 2023). Loss of intellectual abilities interfering with an individual's social and occupational functions. "Four genes (FGFBP2, PRSS23, TGFBR3, NUAK1) out of the 5 top IL-7Rαlow aging genes remained differentially expressed with decreased relative gene expression in the dementia group compared to the MCI group." (PMID 38042785, 2023). "Four genes (FGFBP2, PRSS23, TGFBR3, NUAK1) out of 5 top IL-7Rαlow aging genes remained differentially expressed at the P < 0.05 significance level after Šidák correction with decreased relative gene expression in the dementia group compared to the MCI group." (PMID 37066364, 2023). "Immunohistochemistry staining of formalin fixation and paraffin embedding brain tissues showed that patients with a high TGFBR3 level manifested dementia and obvious Aβ deposition, but patients with low TGFBR3 level did not exhibit dementia and accumulate Aβ." (PMID 35310542, 2021).
glaucoma (4 papers, 2012 to 2024). Increased pressure in the eyeball due to obstruction of the outflow of aqueous humor. "Finally, CDC7 (cell division cycle 7) was identified as a central node in our analysis, and polymorphisms of CDC7/TGFBR3 have been associated with glaucoma, along with visual field progression and a reduction in the thickness of the retinal nerve fiber layer of glaucoma patients." (PMID 39458974, 2024). "Several of the differentially expressed genes have previously been reported to be associated with elevated IOP and/or glaucoma, including MYOC, ADAMTS10, LTBP2, LOXL1, TGFBR3, CYP1B1, and EFEMP15,28,43–45." (PMID 34385434, 2021). "In addition, we identified several transcriptional targets of GLIS1 in TM cells that previously have been implicated in TM-related functions, IOP homeostasis, and ocular hypertension/glaucoma, including MYOC, ADAMTS10, LTBP2, LOXL1, TGFBR3, CYP1B1, and EFEMP15,28,43,44." (PMID 34385434, 2021).
glioma (4 papers, 2020 to 2025). A benign or malignant brain and spinal cord tumor that arises from glial cells (astrocytes, oligodendrocytes, ependymal cells). "Interestingly, TGFBR3 expression differed most notably between glioblastoma and lower-grade gliomas (p < 0.0001)." (PMID 33819300, 2021). "In our study, we observed that TGFBR2 expression was higher in the glioma cell line than TGFBR1 and TGFBR3." (PMID 33576874, 2021).
hepatocellular carcinoma (4 papers, 2020 to 2024). A malignant tumor that arises from hepatocytes. "We selected 2 differentially expressed miRNAs (miR-139-5p and miR-582-3p) and four hub mRNAs (ACVR2B, SMAD2, SMAD5, and TGFBR3) for qRT-PCR verification in 20 hepatocellular carcinoma tissues and 20 adjacent tissues." (PMID 35386287, 2022). "Previous study reported that SULF1 activated the TGF-β/SMAD pathway by binding to TGFBR3 and decreasing the interaction between TGF‐β1 and TGFBR3 in hepatocellular carcinoma." (PMID 38438372, 2024). "The results showed that miR-139-5p and TGFBR3 were significantly down-regulated in hepatocellular carcinoma tissues, and miR-582-3p, ACVR2B, SMAD2 and SMAD5 were up-regulated in hepatocellular carcinoma tissues." (PMID 35386287, 2022). "Similarly, downregulation of TGFBR3 expression in hepatocellular carcinoma (HCC) was driven by HCC cell-derived EVs carrying miR-378b, which increased progression and angiogenesis." (PMID 35493080, 2022).
neuroblastoma (4 papers, 2006 to 2024). Neuroblastoma (NB) is the most common solid, extracranial childhood tumor. "In cancer, a direct interaction between FGFR1 and TGFBR3 has been identified in neuroblastoma cells for which TGFBR3 expression decreases with tumor progression." (PMID 34068954, 2021). "For some genes only circumstantial evidence for a role in neuroblastoma is present (WSB1, CDC42, PLAGL1, PRAME and TGFBR3); that we identified these genes in the present study warrants further investigations into their possible role in neuroblastoma development." (PMID 16989664, 2006).
Sepsis (4 papers, 2020 to 2024). Sepsis is defined as life-threatening organ dysfunction caused by a dysregulated host response to infection. "Furthermore, the hub genes TLR5, FCGR1A, ELANE, GNLY, IL2RB and TGFBR3, which may be associated with the prognosis of sepsis, and their negatively correlated microRNAs, were analysed." (PMID 35332254, 2022). "The primary finding in this research was that lncRNA H19 inhibited inflammation in sepsis-induced ALI by regulating the miR-107/TGFBR3 axis." (PMID 36180862, 2022). "LncRNA H19 inhibited LPS-induced PMVEC apoptosis and pro-inflammatory cytokine production and attenuated sepsis-induced ALI by targeting TGFBR3 as the ceRNA of miR-107." (PMID 36180862, 2022). "TGFBR3 is a pivotal gene that is downregulated in sepsis, and TGFBR3 participates in the regulation of inflammation in ALI." (PMID 36180862, 2022). "This study aimed to investigate the mechanism of H19 in alleviating sepsis-induced ALI through the miR-107/TGFBR3 axis." (PMID 36180862, 2022). "miR-107 is highly-expressed and TGFβ type III receptor (TGFBR3) is poorly-expressed in sepsis, yet their roles in sepsis development require further investigation." (PMID 36180862, 2022). "In conclusion, the present study highlighted that lncRNA H19 ameliorated apoptosis and inflammation in sepsis-induced ALI through the miR-107/TGFBR3 axis." (PMID 36180862, 2022). "In the two groups of different expression trend modules, the core genes such as CD160, GATA2, GNLY, IL2RB and TGFBR3 were downregulated in the sepsis group, while genes such as ELANE, IL1R1, TLR5, FCGR1A, MAPK14 and PCSK9 were upregulated." (PMID 35332254, 2022). "It showed association with CD2, IL2RB, and IL7R in adult SIRS and KLRG1 and TGFBR3 in adult sepsis, among others." (PMID 32318053, 2020). "In reviewing the literature, TGFBR3 was found downregulated in sepsis." (PMID 36180862, 2022). "Consequently, the genes TLR5, FCGR1A, ELANE, GNLY, IL2RB and TGFBR3 genes were ultimately identified as hub genes in sepsis." (PMID 35332254, 2022). "Hence, we hypothesized that lncRNA H19 limited inflammatory responses in sepsis-induced ALI through the miR-107/TGFBR3 axis." (PMID 36180862, 2022). "The Venn diagram shows that a total of eight overlapping genes were discovered between ACSL4 co-expression genes and sepsis, including GK, CLEC4E, ACSL1, TGFBR3, ADAM9, AZI2, BCAT1, and CYP1B1." (PMID 39262873, 2024). "We found that lncRNA H19 was poorly-expressed in the mouse model and cell model of sepsis-induced ALI, while overexpression of H19 suppressed apoptosis and inflammation in sepsis-induced ALI in vivo and in vitro, in which the miR-107/TGFBR3 axis was involved." (PMID 36180862, 2022). "In addition, the TGFβ type III receptor (TGFBR3) is an ALI-related gene and an important gene that is downregulated in sepsis." (PMID 36180862, 2022). "One major drawback of the study is the lack of sufficient investigation into the regulatory mechanism of lncRNA H19 in inflammation in sepsis-induced ALI, for example, through modulating several signaling pathways downstream of TGFBR3, which we plan to include in future studies." (PMID 36180862, 2022).
clear cell renal cell carcinoma (3 papers, 2019 to 2021). "The loss of TGF-beta Receptor III (TGFBR3) expression primes clear-cell renal cell carcinoma cells with facilitated metastatic potential by diminishing TGF-β2 signaling, which was implicated in poor prognosis of patients." (PMID 31307515, 2019). "The tumor suppressive role of TGFBR3 has been proven in multiple malignancies including clear-cell renal cell carcinoma, in which the loss of TGFBR3 expression was found to be significantly involved in the tumor formation and metastasis through TGF-β-mediated mechanism." (PMID 31307515, 2019). "TGFBR3 was a strong positive predictor of survival in both renal clear cell carcinoma (HR = 0.46, p = 2.1E-7) and renal papillary cell carcinoma (HR = 0.53, p = 0.042)." (PMID 33819300, 2021). "Interestingly, this trend was also repeated in renal clear cell carcinoma, where INHA was only a predictor of survival in TGFBR3 low (HR = 2.75, p = 9.0E-06) and ENG low (HR = 2.6, p = 2.5E-06)." (PMID 33819300, 2021).